C7 (complement C7)
Diseases named in the same sentence as C7 in open-access papers (continued):
Sharing a sentence is not in itself a finding about the gene and the disease.
tumor (29 papers, 2006 to 2025). "Reduced C7 mRNA levels are associated with advanced cancer stages and higher tumor grades in patients with HCC." (PMID 40612108, 2025). "C7 encodes a complement protein C7 that forms a membrane attack complex with other complement components and is recognized as a potential tumor suppressor." (PMID 33428680, 2021). "Among downregulated genes in classical tumours compared to preinvasive lesions, C7 encodes for a component of the complement cascade and its reduced expression has been reported as a poor prognostic marker in several malignancies." (PMID 31439856, 2019). "The results showed that CAFs in P-LNs were associated with the high expression of NFIB, IGLC2, IGHG4, C7, and CCL19, while CAFs in tumor 3 had high expression of DIO2, LGALS1, WNT5A, NEAT1, and MMP11 in the tumor." (PMID 36569924, 2022). "Consistently, the expressions of C7 and C9 in tumor tissues were confirmed to be downregulated in tissue microarray (TMA) compared with adjacent normal tissues." (PMID 35929594, 2022). "In situ hybridization confirmed the localisation of C7 mRNA in normal oesophageal epithelial cells and its disappearance in tumour cells." (PMID 16969345, 2006). "Moreover, GP1 displayed increased expression of angiogenic features (e.g., ANGPTL4, EGFR, AAMP) and complement and coagulation cascade components (e.g., C1, C7, C8, C9, PLG, SERPINE1), which have been associated with aggravated tumor invasion." (PMID 35440542, 2022). "For example, genes related to the GO term “components of complement,” such as C1QA, C1QB, and C7, may promote tumorigenesis in cells within the tumor microenvironment." (PMID 34557425, 2021). "In fact, C7, as a single molecule, may play limited roles in tumor progression." (PMID 34631552, 2021). "The differential analysis also confirmed the high expression of CD74, HLA-DRA, C7, CCL12, and CCR3 in CAFs from P-LN but lower expression of VIM, APOD, MMP11, TAGLN, and CDKN2A compared with that in the primary tumor." (PMID 36569924, 2022). "In total, 45 tumor microenvironment (TME)-related DEGs were identified, of which Complement C7 (C7) was selected and validated as a hub gene." (PMID 32984006, 2020). "And the immunostaining of C7 was high in tumor cells but much weaker in non-neoplasm in the same section, which was further confirmed by Western blot analysis based on frozen IDC specimens and non-neoplastic breast specimens." (PMID 34631552, 2021). "Furthermore, complement C3, C3a, C4, C4a, and C7 have been identified as biomarkers in HCC diagnosis while C7 and CFH are recognized for their critical roles in mediating stemness of tumor-initiating cells." (PMID 33718121, 2020). "Human SAMD9, a tumor suppressor and a restriction factor for poxviruses in cell lines, is antagonized by two classes of poxvirus proteins, represented by vaccinia virus (VACV) K1 and C7." (PMID 29447249, 2018). "The results revealed that expression levels of SLCO4C1, POU4F1, DNASE1L2, WDR72, LPO, and C7 in tumor tissues were significantly higher than those in normal tissues, while the expression differences of SLC4A4, CELF4, and SLC11A1 were not statistically significant." (PMID 37745305, 2023). "Then, C7 protein expression was examined by our IHC analysis in 331 cases of IDC, 45 cases of DCIS, and 52 cases of non-neoplastic tissues adjacent to tumor." (PMID 34631552, 2021).
cancer (23 papers, 2012 to 2025). A tumor composed of atypical neoplastic, often pleomorphic cells that invade other tissues. "These included CALB1, AURKB, SEPT14, and the histone-coding gene HIST1H1B and downregulated ADH1B and C7 in 11 cancer types." (PMID 38763334, 2024). "Interestingly, there was significant upregulation of complement components C7 and C6 which form parts of the Membrane Attack Complex that inserts into the membranes of cells (e.g., cancer cells) during complement-mediated cell death." (PMID 37435088, 2023). "Since common sites for canine HSA are spleen and liver, which both contain large numbers of immune cells, it could be surmised that modulation of inflammatory responses is a key function of complement C7 in this cancer and hence, the upregulation." (PMID 33673507, 2021). "The Complement component 7(C7) located on chromosome fragment 5p13.1–13.3, which might involve in the progression of cancer if the copy number variated." (PMID 33964921, 2021). "Moreover, C7 mRNA expression in the prostate ranked as the bottom fifth across all the types of cancer cell lines." (PMID 32984006, 2020). "Moreover, the C7 mRNA expression level in cancer tissues was an independent predictor for both disease progression and death in patients with NSCLC." (PMID 27852032, 2016). "However, additional genes linked to cancer processes were found deregulated in this study including AHRR, C7, CLPTM1L, and MRPS30 involved in apoptosis, CDH6 in cell adhesion and CEP72 in the cell cycle." (PMID 22412903, 2012). "Therefore, it is concluded that the reduction of C7 expression in tumors prevents the lysis of abnormal cells, enhances the resistance of cancer cells against complement attack, aggravates the inflammation around tumors and finally promotes the malignant progression." (PMID 27852032, 2016). "The common (pan-cancer) genes are MMP11 (+), C7 (-), ANGPTL1 (-), UBE2C (+), IQGAP3 (+) and ADH1B (-)." (PMID 36802377, 2023). "In contrast, DCN (chr12q21.33), LIFR (chr5p13.1), ABCA8 (chr17q24.2), C7 (chr5p13.1) and ZEB2 (chr2q22.3) on predicted PCSRs were down-expressed in 9, 7, 8, 8 and 8 cancers, respectively." (PMID 24796549, 2014). "For example, ADT levels of EPCAM on cancer/epithelial cells (c0, c4, c8, c14 and c15), CD31 (PECAM1) and CD34 on endothelial cells (c7 and c9), CD146 (MCAM) on perivascular cells (c11), CD90 (THY1) and CD34 on CAFs (c13) and CD45 (PTPRC) on immune cells (c3, c5 and c12)." (PMID 33971952, 2021). "The killing of the SW480 cancer cells was complement dependent, since the cells were not killed by human serum that was depleted of complement activity through heat-inactivation or removal of C7, a critical component of the MAC." (PMID 31889898, 2019).
infection (19 papers, 2012 to 2025). The state of being infected such as from the introduction of a foreign agent such as serum, vaccine, antigenic substance or organism. "In comparing the groups with and without infection, the SNPs most significantly associated with infection were located in complement genes, including C3, C5, C6, C7, C9 and MBL2 (P < 10−6)." (PMID 27063552, 2016). "Complement is a humoral factor of innate immunity and plays a crucial role in the fish immune response to pathogen infection, including C1q, C3, C5b, C6, C7, C8, C9, etc.." (PMID 41154820, 2025). "Our study shows how S. chrysophrii infection changes the abundance of several complement proteins (factor H, factor B, factor I, C1q, C3, C4, C5, C6, C7, C8), inducing an inhibition of the alternative pathway as the infection intensity increases." (PMID 36088326, 2022). "The C7 complement gene was upregulated at 6, 12, and 24 hours and downregulated at 48 hour after infection in the planktonic group." (PMID 35677656, 2022). "Nevertheless, the infection was also able to repress extracellular exosome-related genes, such as complement C7 (C7) in the R line of the HSF flock, and fibroblast growth factor 9 (FGF9), cadherin 16 (CDH16), and FGG, in the R line of the TSF flock." (PMID 30678719, 2019). "Vaccinia C7 protein level in infected cells was used to verify infection and drug effects." (PMID 37217469, 2023). "However, only VACV∆C7L infection induced Ifnb1 gene expression, indicating that C7 is a negative regulator of the cytosolic dsRNA-sensing pathway." (PMID 35351885, 2022). "Blocking C7 is likely to be less of an infection hazard compared to C5 blockade because C5a-mediated neutrophil recruitment is unimpaired - indeed, the majority of patients with C7 deficiency are healthy, although at increased risk of Neisserial infections; iv)." (PMID 33424866, 2020). "Of the top 20 contributing proteins for each infection identified by machine learning, 6 were found to be common to both LD and WNV (APOD, C4BPB, C7, HP, ITIH3, PGLYRP2), but with varying degrees of importance in each disease." (PMID 36569838, 2022). "In addition, the expression of c1ql2, C3, C5, C7, C9, CFB, and complement factor H (CFH) was regulated in rainbow trout stimulated with β-glucan upon infection with A. salmonicida, suggesting improved immune enhancement." (PMID 34835165, 2021). "In addition, at least 11 genes implicated in complement activation were significantly impacted by infection in CHB, such as complement factor properdin (CFP, 2.8 fold), complement component 7 (C7, 4.2 fold), and complement factor I (CFI, 12.1 fold)." (PMID 27197554, 2016).
bacterial infection (3 papers, 2014 to 2019). "In fact, polymorphisms in C7 (for soluble membrane attack complex formation) and mannan-binding lectin, were associated with bacterial infection and with decreased levels of recipient C7 protein expression, soluble membrane attack complex, and IL-1β." (PMID 31547621, 2019).
adenocarcinoma (2 papers, 2020 to 2025). A common cancer characterized by the presence of malignant glandular cells. "Expression of most complement system members was increased at least in some tumors, while mRNA of C7 was reduced in each of the ten investigated adenocarcinomas compared to the respective normal tissue." (PMID 33628739, 2020).
C7 also shares sentences with these, for which no sentence is quoted: diabetic retinopathy (2 papers); lung carcinoma (2); age-related macular degeneration (1); Arthritis (1); asthma (1); atypical hemolytic-uremic syndrome (1); autoimmune disease (1); co-infection (1); coronary artery disease (1); hip fracture (1); infectious disease (1); Insulin resistance (1); legionellosis (1); liver cancer (1); lung adenocarcinoma (1); myopia (1); pancreatic ductal adenocarcinoma (1); periodontitis (1); protein deficiency (1); skin disorder (1); small cell carcinoma (1); squamous cell carcinoma (1); α-synucleinopathy (1).